KLF4 (KLF transcription factor 4)
Diseases named in the same sentence as KLF4 in open-access papers (continued):
Sharing a sentence is not in itself a finding about the gene and the disease.
leukemia (37 papers, 2014 to 2026). A malignant (clonal) hematologic disorder, involving hematopoietic stem cells and characterized by the presence of primitive or atypical myeloid or lymphoid cells in the bone marrow and the blood. "Mechanistically, the acceleration of leukemia was linked to the upregulation of the mitogen-activated kinase MAP2K7 because the loss of KLF4 released repression of the Map2k7 gene." (PMID 39717752, 2024). "Our previous work showed that loss of the pioneer factor KLF4 in a NOTCH1-induced T-ALL mouse model accelerated the development of leukemia through expansion of leukemia-initiating cells and activation of the MAP2K7 pathway." (PMID 34504651, 2021). "Loss- and gain-of-function experiments in leukemia cells demostrated that KLF4 controls monocyte differentiation." (PMID 27669739, 2016). "In lymphomas and leukemias, mutations in this region may inhibit ubiquitination and degradation of KLF4 in tumors, contributing to malignant progression." (PMID 39995670, 2025). "Indeed, several mRNAs associated with the development of leukaemia, including Dusp6, Klf4, and Plxnb2, were significantly elevated in ECs and resting leukaemia cells after chemotherapy." (PMID 38674015, 2024). "As a result, loss of Fbw7 could cause accumulation of the Klf4 transcription factor, which might subsequently block the proper differentiation process, leading to the development of leukemia." (PMID 25116380, 2014). "Our group investigated the role of KLF4 in leukemia stem cells using mouse models developed through the retroviral transformation of hematopoietic stem/progenitor cells and transplantation." (PMID 40589762, 2025). "In this review, we will summarize studies from our group that utilized conditional Klf4 deletion and retroviral transduction models with oncogenes to investigate their role in leukemia stem cells (LSC) within lymphoid and myeloid leukemia." (PMID 40589762, 2025). "In B-cell lymphoma and various leukemia lineages, KLF4 expression is markedly reduced, potentially due to promoter hypermethylation observed in several hematologic malignancies." (PMID 39995670, 2025). "A gene expression profiling analysis in pediatric leukemia indicates that KLF4 is significantly downregulated in T-ALL compared to normal bone marrow, particularly in T-ALL subtypes associated with the worst prognosis." (PMID 40589762, 2025). "APTO-253, a targeted inducer of KLF4, have been found in a clinical trial to have successfully halted the progression of some advanced tumors, especially leukemia." (PMID 37031197, 2023). "Differential gene expression analysis found that many upregulated genes in the C2 subtype were associated with increased leukemia cell survival, proliferation, and drug resistance, such as S100A8, S100A9, LILRB3, KLF4, LST1, and ITGB2." (PMID 37691822, 2023). "KLF4 is one of the Yamanaka factors able to induce pluripotent stem cells and was recently shown to promote leukemia stem cell division and stemness." (PMID 37143070, 2023). "RUNX1 inhibits proliferation and induces apoptosis via KLF4-mediated transactivation of P57 in leukemia cells." (PMID 38057816, 2023). "Correspondingly, the transcript-level expressions of stem cell-associated genes, including OCT4, KLF4, BMI1, NANOG and SOX2, were significantly increased in leukemia cells upon treatment with exosomes from BM-MSCs." (PMID 33789743, 2021). "Altogether, these observations highlight a need to better define the role of KLF4 in leukemia and in particular AML." (PMID 33659038, 2021). "When MRD was achieved (defined as less than 1% leukemia cells in the bone marrow) chemotherapy was discontinued and Dox was administered to induce KLF4 expression during the phase of tumor regrowth." (PMID 32944247, 2020). "HAP1 cells originate from experiments to induce pluripotency in the leukemia KBM7 cell line by transduction with KLF4, POU5F1 (Oct4), SOX2, and MYC." (PMID 33228647, 2020).
leukemia (continued). "In competitive preclinical in vivo trials, we found that re-expression of wild type KLF4 reduced the leukemia load in PDX models of B-ALL, with the strongest effects being observed after conventional chemotherapy in minimal residual disease (MRD)." (PMID 32944247, 2020). "Sox2 and Klf4, instead of c-Myc, appear to play a major role in the elimination of leukemia cells, at least for the leukemia type tested in our study." (PMID 31811153, 2019). "Dissection of the functional effects of OSKM shows that Klf4 and Sox2 play dominant roles compared to c-Myc and Oct4 in elimination of leukemia cells." (PMID 31811153, 2019). "It exerts a powerful anti-leukemic effect by regulating microRNA and gene targets, suggesting that KLF4 functions as a tumor suppressor in leukemia." (PMID 30285885, 2018). "Here, we demonstrated that NPM1-mA inhibited myeloid differentiation of leukemia cells in vitro, and that the miR-10b/KLF4 axis was involved in this process." (PMID 27669739, 2016). "Among the targets predicted, KLF4 is of particular interest as it promotes myeloid differentiation in leukemia." (PMID 27669739, 2016). "To further investigate the function and mechanism of HDAC1 and Klf4 in leukemia cells, we performed tumorigenesis experiments in BLAB/c nude mice." (PMID 25341045, 2014). "Further, knockdown of HDAC1 in leukemia cells K562, HL-60, and U937 significantly increased Klf4 expression and inhibited cell cycle progression and cell proliferation, similar results were found for HDAC inhibitors (VPA and mocetinostat)." (PMID 25341045, 2014). "This review summarizes the key findings regarding KLF4 in normal blood cells and leukemia." (PMID 40589762, 2025). "In leukemia, KLF4 may inhibit or promote self-renewal in leukemic stem cells, depending on oncogenic signals and KLF4’s dual role as a transcriptional activator and repressor." (PMID 40589762, 2025). "KLF4 may also play a regulatory role in cutaneous squamous cell carcinoma, lymphoma, leukemia and cervical cancer." (PMID 37031197, 2023). "Collectively, these data suggest pharmacological inhibition of KLF4 downstream targets may represent an alternative to control leukemia burden." (PMID 33659038, 2021). "Although these findings have fueled a presumption of tumor-suppressive function for KLF4 in AML, a model of ZMYM2-FGFR1 leukemia suggests KLF4 may be involved in AML leukemogenesis." (PMID 33659038, 2021). "It will be important to define also whether KLF4 is upregulated in leukemic clones emerging in refractory or relapsed leukemia because high levels of expression of KLF4 were found in leukemic clones in a relapsed patient with chronic lymphocytic leukemia." (PMID 33659038, 2021). "Supporting a suppressive role in leukemia, KLF4 inhibits T-cell acute lymphoblastic leukemia (T-ALL) and KLF4 expression is silenced in pediatric T-ALL by CpG promoter methylation, which was associated with aberrant expression of MAP2K7, a kinase pathway that accelerates disease progression." (PMID 33659038, 2021). "Indeed, exogenous expression of KLF4 significantly induced G1 phase cell cycle arrest and suppressed the growth of leukemia cells in two different AML cell lines, THP-1 and KO52." (PMID 33219287, 2020). "Furthermore, colony assay demonstrated that overexpression of Sox2 or Klf4 alone significantly reduced the clonal growth of leukemia cells in vitro." (PMID 31811153, 2019). "Here, we test whether leukemia cells can be reprogrammed in vivo using the canonical reprogramming transcription factors-Oct4, Sox2, Klf4, and c-Myc (termed as OSKM)." (PMID 31811153, 2019). "KLF4 expression has been reported in different leukemia and B-lymphocyte lymphoma cell lines." (PMID 31040909, 2019). "In the present study, we identified KLF4 as a direct target of miR-10b in leukemia cells." (PMID 27669739, 2016).
leukemia (continued). "Interestingly, CCR7 that regulates CNS infiltration in T-ALL and CXCR4, which is essential for stem cell and leukemia cell localization were both repressed upon KLF4 overexpression in Jurkat cells." (PMID 25644173, 2015). "To investigate the significance of Class I HDACs (HDAC1, HDAC2, HDAC3, and HDAC8), HDAC11, and Klfs (Klf1, KLf3, Klf4, and Klf7) in the pathogenesis of human leukemia, we used real-time RT-PCR to evaluate the expression of HDACs and Klfs in bone marrow samples from human leukemia patients." (PMID 25341045, 2014). "In our study, modulation of Klf4 expression can mimic the effects of HDAC1 in leukemia cells." (PMID 25341045, 2014). "Additionally, we found that Klf4 was significantly downregulated in leukemia patients and more negatively correlated with FAB type." (PMID 25341045, 2014). "The in vivo tumorigenesis results provide more evidences that the inhibition of HDAC1, overexpression of Klf4, or a combination of the two may provide a novel way to treat leukemia in humans." (PMID 25341045, 2014). "Also, KLF4 suppresses tumor progression in ovarian cancer, melanoma, leukemia and cervical cancer." (PMID 37031197, 2023). "The observed ‘unstable CML disease’ was also seen when deletion of the Klf4 gene was induced after transformation, transplantation, and establishment of myeloid leukemia cells, which suggests that regression of leukemia was not due to differential homing of Klf4-deficient cells into bone marrow." (PMID 33067577, 2020). "Interestingly, Ezh2 inactivation has been also observed in leukemia and Klf4 may function as a tumor suppressor gene in leukemia." (PMID 28078190, 2017). "Moreover, overexpression or knockdown of Klf4 could markedly block the effects of HDAC1 overexpression or knockdown on leukemia cells in vitro and in vivo, respectively." (PMID 25341045, 2014). "elucidated multiple mechanisms by which KLF4 regulates MICA expression and enhances NK cell anti‐leukemia activity." (PMID 41532367, 2026). "The conditional deletion of the Klf4 gene accelerated leukemia in the NOTCH1-induced T-ALL mouse model, increasing both the proliferation of T-ALL cells and the frequency of leukemia-initiating cells (LIC) measured in a limiting dilution transplantation study." (PMID 40589762, 2025). "A total of 100 TFs with silenced promoters were downregulated relative to AML, including hematopoietic regulators and genes known to be involved in leukemia, such as CEBPA, CEBPD, KLF4, IRF4 or MEIS1." (PMID 38972954, 2024). "To address the significance of KLF4 expression in AML, we deleted the KLF4 gene in the MM6 cell line, which represents MLL-rearranged leukemia, and the NB4 cell line which represent PML-RARα PML using CRISPR-Cas9 technology." (PMID 33659038, 2021). "We show that Aza upregulates KLF4 in B-ALL, which mediates, at least in part, the anti-leukemia effect of Aza; this result is of major translational importance." (PMID 32944247, 2020). "For all cell types, co-occurring TF pairs are not just combinations of the single TFs, moreover the co-occurring TF pairs include more cell-type specific TFs such as KLF4 and cMYC in ESCs or tumor-related genes STAT5 and TAL1 in leukemia." (PMID 30142147, 2018). "KLF4 plays an important role in non-solid tumors (e.g., lymphoma and leukemia), with its functions again dependent on tumor type and co-regulatory mechanisms." (PMID 39995670, 2025). "Therefore, our results highlight miR-10b and KLF4 as potential therapeutic targets and novel prognostic markers for NPM1-mA positive leukemia." (PMID 27669739, 2016). "Modulation of Klf4 levels by altering shRNA or using an ectopic expression vector can mimic the effects of HDAC1 on cell proliferation, cell cycle, and the expression level of p21 and p27 in human leukemia cell lines K562, HL-60, and U937." (PMID 25341045, 2014).
leukemia (continued). "However, experiments of knocking down DDX58 in Klf4 knockout MLL-AF9-induced leukemia suggested that elevated levels of DDX58 in Klf4 knockout LSCs did not contribute to impaired LSC frequency despite reducing clonogenicity in methylcellulose." (PMID 40589762, 2025). "Moreover, developing tools to pharmacologically stimulate the KLF4-DPYSL2A axis in leukemia cells should be enthusiastically explored to establish a novel “differentiation therapy” for patients with AML." (PMID 33219287, 2020). "The lack of mutations and genetic alterations suggest that KLF4 may be required for disease progression whereas studies using the Cancer Genome Atlas have shown that KLF4 expression is not uniform among AML patients, but is generally lower than normal blood cells and associated with leukemia stage." (PMID 33659038, 2021). "During these processes, KLF4 stimulates the formation of open chromatin and directly establishes de novo chromatin loops independently of CTCF65,66, possibly explaining changes in the 3D structure of CIMP leukemias that do not co-occur with variations in CTCF binding." (PMID 38972954, 2024).
osteosarcoma (34 papers, 2016 to 2025). A usually aggressive malignant bone-forming mesenchymal neoplasm, predominantly affecting adolescents and young adults. "The expression of KLF4 is highly associated with stemness in human osteosarcoma carcinomas." (PMID 37590265, 2023). "Thus, KLF4 expression was associated to the development of drug-induced stemness phenotypes in osteosarcoma cells via a mechanism that seems to be mediated by the activation p38 MAPK signaling and can be inhibited by statins." (PMID 34198693, 2021). "Given that KLF4 played an important role in osteosarcoma tumorigenesis, we speculated that it might associate with upregulting CRYAB expression." (PMID 27105535, 2016). "Interestingly, KLF4 is also strongly associated with cancer stemness; for example, KLF4 promotes the formation of spheres, the transcription of stemness-associated genes, and chemoresistance in human osteosarcoma cells." (PMID 38916835, 2024). "KLF4 was shown to contribute to chemoresistance in osteosarcoma partially through regulation of the high-mobility group box 1 (HMGB1)." (PMID 39685635, 2024). "Our recent work has indicated that LINC00629 plays an oncogenic role in osteosarcoma by elevating KLF4 stability." (PMID 37528150, 2023). "In osteosarcoma and glioma, CSCs acquire a higher self-renewal and sphere-formation ability through the KLF4-activated MAPK signaling pathway." (PMID 37853437, 2023). "Our results demonstrate that the overexpression of lncRNA SOX21-AS1 up-regulates mTOR and KLF4 by sponging hsa-mir-7-5p and hsa-mir-145-5p, and ultimately regulates the proliferation of osteosarcoma." (PMID 34696664, 2022). "Further mechanistic studies indicated that LINC00629 interacted with KLF4 and suppressed its degradation, which led to a KLF4 increase in osteosarcoma." (PMID 36539799, 2022). "Overexpression of CRYAB expression in osteosarcoma is regulated through krüppel-like factor 4 (KLF4), a zinc-finger transcription factor." (PMID 36077137, 2022). "In this study, we demonstrated that the overexpression of lncRNA SOX21-AS1 upregulated mTOR and KLF4 through sponging hsa-mir-7-5p and hsa-mir-145-5p, and ultimately promoted osteosarcoma proliferation." (PMID 34696664, 2022). "Our results prove that overexpression of lncRNA SOX21-AS1 up-regulates mTOR and KLF4 through sponging miR-7-5p and miR-145-5p, and ultimately promotes the proliferation of osteosarcoma." (PMID 34696664, 2022). "Conversely, KLF4-overexpressing cells were more chemoresistant and metastatic, and osteosarcoma stem cells had increased levels of KLF4." (PMID 34680284, 2021). "Adriamycin treatment has been shown to induce a stem-like phenotype and promote metastatic potential in osteosarcoma cells by upregulating the Yamanaka factor KLF4." (PMID 34303383, 2021). "KLF8 is a dual transcription factor and can either suppress or activate the transcription of target genes, including cyclin D1, KLF4 and E-cadherin, which are related to tumor development in diverse cancer types including osteosarcoma." (PMID 33817271, 2020). "Consistent with our findings, Li, et.al., reported that statins dramatically reduced CSC properties and metastasis in osteosarcoma by downregulating KLF4." (PMID 31526394, 2019). "The down-regulation pattern of oncogenic gene expression, namely c-Myc and Klf4 in both H103 and H376 were also observed in reprogrammed human osteosarcoma cells." (PMID 28417059, 2017). "We also observed downregulation of transcription factors AHR (Aryl Hydrocarbon Receptor), FOSB (FBJ Murine Osteosarcoma Viral Oncogene), and KLF4 (Kruppel-Like Factor)." (PMID 29123522, 2017). "In this study, we identified that the expression of KLF4 was markedly increased in osteosarcoma tissues compared with the normal bone tissues." (PMID 27105535, 2016). "In additional, we found that KLF4 enhanced osteosarcoma cell proliferation and migration through elevating CRYAB expression." (PMID 27105535, 2016).